ATG7 (autophagy related 7)
Diseases named in the same sentence as ATG7 in open-access papers (continued):
Sharing a sentence is not in itself a finding about the gene and the disease.
breast cancer (continued). "Thus, in the present study, we demonstrate that ATG7 is an important determinant in the regulation of breast cancer progression through cellular crosstalk between cancer cells and their environmental stromal components." (PMID 40707430, 2025). "However, the role of ATG7 in regulating autophagy in breast cancer progression requires further elucidation." (PMID 40707430, 2025). "In addition, advanced TNM stage breast cancer patients exhibited lower ATG7 protein expression in the stroma." (PMID 40707430, 2025). "However, further examination of primary fibroblasts derived from breast cancer patients by GEO database analysis of GSE29270 indicated that CAFs showed significantly lower ATG7 expression than normal fibroblasts." (PMID 40707430, 2025). "Breast cancer is also regulated by Atg7-relevant miRNAs, including miR-1275 and miR-348110." (PMID 38553562, 2024). "Selaginella trichoclada-derived robustaflavone A induces ferroptosis by downregulating the expressions of acyl-CoA synthetase long-chain family member 4 (ACSL4), ACSL5, STEAP3, lysophosphatidylcholine acyltransferase (LPCAT3), and autophagy-related 7 (ATG7) genes in breast cancer cells." (PMID 36612314, 2023). "In the current study, we originally aimed to co-delete Palb2 and Atg7 in the mammary gland using Cre recombinase driven by the promoter of whey acidic protein (Wap-Cre), to further study the role of autophagy in PALB2-associated breast cancer." (PMID 35404932, 2022). "Besides, ATG7 can contribute to the survival of dormant breast cancer cells and metastatic tumor recurrence by activating autophagy." (PMID 36203871, 2022). "Moreover, the accumulation of autophagosomes with concomitantly elevated mRNA levels of ATG7 leads to radiation resistance in breast cancer under hypoxic exposure." (PMID 36105209, 2022). "Indeed, autophagy inhibition via silencing ATG7 or 12 in breast cancer cells resulted in an increase in FA size that was paralleled by a decreased migration rate, indicating that autophagy reduced migration by stabilizing FA." (PMID 34207792, 2021). "In addition, autophagy-related 7 (ATG7) has also been involved in survival of dormant breast cancer cells." (PMID 33498251, 2021). "In this study, we demonstrate that ERBB2 promotes autophagy by upregulating ATG12 as well as other autophagy-related (ATG) proteins including ULK1, FIP200, ATG5, and ATG7, leading to breast cancer treatment resistance and worse outcome to patients with ERBB2-positive breast cancer." (PMID 33801244, 2021). "In breast cancer, autophagy inhibition through ATG7 or Beclin1 knockdown altered IL-6 secretion." (PMID 27933272, 2016). "In addition, the invasive phenotype of HRASV12-transformed breast cancer cells is reduced in ATG7 knockdown cells." (PMID 27933272, 2016). "On one hand, ATG7 suppresses resistance of human breast cancer cells to photodynamic therapy." (PMID 26404030, 2015). "Thus, from this perspective, abnormally low ATG7 expression in the stromal fibroblasts of breast cancer tissue should disturb the autophagy balance of tumor tissue, which would also facilitate tumor progression and challenge cancer treatment by remodeling the TME." (PMID 40707430, 2025). "Consequently, these findings prompt us to consider that the expression level of ATG7 in fibroblasts might hold greater relevance in influencing the progression of breast cancer." (PMID 40707430, 2025). "Therefore, to confirm these clinical observations and explore the molecular mechanism of patient relapse, we first examined the effect of Atg7 expressed in fibroblasts on the progression of breast tumors in an orthotopic mouse model of spontaneous breast cancer metastasis." (PMID 40707430, 2025). "However, the role of ATG7 in fibroblasts in regulating breast carcinoma remains poorly understood." (PMID 40707430, 2025).
breast cancer (continued). "In detail, inhibiting autophagy by using HCQ or by knocking out ATG7 in dormant metastatic breast cancer cells reduced mitophagy, leading to the accumulation of damaged mitochondria and ROS, which decreased the viability of dormant breast cancer cells and prevented the dormancy to growth switch." (PMID 34207792, 2021). "More specifically, autophagy-related 7 (ATG7) has been identified to be essential for activation of autophagy in vivo; knockdown of ATG7 was shown to decrease metastatic burden while autophagy blockade specifically targeted dormant breast cancer cells leading them towards apoptotic cell death." (PMID 31817646, 2019). "For example, deletion of Atg7 and Beclin1 inhibited autophagy induced by nutrient deprivation of cervical cancer cells and induced cell death while stable knockdown of Atg7 in human breast cancer cells inhibited cell growth in soft agar and tumor formation in nude mice." (PMID 23772420, 2013). "To examine the effect of fibroblasts on breast cancer cells through paracrine crosstalk, we treated 4T1 and MDA-MB-231 cells with prepared conditioned medium (CM) from WT and Atg7−/− MEFs and then examined cell proliferation." (PMID 40707430, 2025). "The induction of autophagy gene ATG7 and the conversion of autophagy markers (LC3-I and LC3-II) and Tspan28, Tspan29, and Tspan30 in rotenone-treated prostate and breast cancer stem cells were detected by Western blotting." (PMID 38649381, 2024). "Atg7f/f;Wap-Cre (Atg7-CKO) mice had slightly shorter overall survival (T50 = 604 days); 1 of the 22 mice (4.5%) developed mammary tumor and 9 (45.5%) developed other tumors." (PMID 35404932, 2022). "Fulvestrant-resistant breast cancer sublines, established from the MCF-7 cell line, have been shown to have high levels of autophagy with notable ATG7 upregulation and increased LC3-II/LC3-I ratio." (PMID 36077830, 2022). "Furthermore, ATG7 levels may also be of prognostic value in breast cancers patients." (PMID 34725936, 2021). "EMP3 knockdown reduced expression of ATG7, phosphorylated P62, and LC3A/B-II, while EMP3 overexpression upregulated these proteins, demonstrating that EMP3 promotes breast cancer cell autophagy." (PMID 34511602, 2021). "One present study revealed that rapamycin significantly promoted the apoptosis of breast cancer cells induced by DHA, but this effect will be reduced following Atg7 knockdown." (PMID 33613116, 2021). "In breast cancer, BECN and ATG7 mediated autophagy is considered as a means of evading apoptosis following DNA damage, thus prolonging cell survival." (PMID 33363019, 2020). "Multiple breast cancer cells, MDA-MB-231, SUM149, MDA-MB-468, and SUM159 showed increased expression of pATG1, ATG5, ATG7 and BECN1 proteins in a temporal manner in response to HNK treatment." (PMID 32963809, 2020). "was found to induce autophagic cell death in HER2-overexpressing BT-474 breast cancer cells leading to a vacuole formation and increasing levels for autophagy markers (e.g., LC3A/B, ATG3, ATG7, and ATG16L) in human breast cancer cells." (PMID 27537898, 2016). "Dormant breast cancer stem-like cells induced by farnesyl transferase inhibitors expressed high levels of autophagy markers, such as ATG5, ATG7, and ATG12." (PMID 26458814, 2015). "Besides, miR-6803b in ATG7−/− HFF-1 cells can indeed be packaged into exosomes and absorbed by recipient human breast cancer cells—MDA-MB-231." (PMID 40707430, 2025). "Furthermore, miR-217 induces HSF1/ATG7 pathway signaling by limiting NF1 expression and enhancing breast cancer cell autophagy, leading to chemoresistance." (PMID 38553562, 2024).
breast cancer (continued). "Combination therapy with the autophagy inhibitor 3-MA and trastuzumab showed a better effect in HER2-positive breast cancer cells, and inhibition of the autophagy-related factors ATG5, ATG7, and Beclin1 reduced resistance to tamoxifen in ER-positive breast cancer." (PMID 36831614, 2023). "Over-expression of circCDYL promoted proliferation of HER2+ breast cancer cells but not through miR-1275-ULK1/ATG7-autophagic axis." (PMID 34395434, 2021). "Moreover, ATG4, ATG7, and the ATG8 homologs are responsible for metabolic homeostasis in dormant breast cancer cells by activating the autophagic pathway." (PMID 34207792, 2021). "Similarly, hsa_circ_0092276, which sponges miR-384, regulates ATG7 expression and promotes DOX resistance in breast cancer." (PMID 35070998, 2021). "Meanwhile, rapamycin could promote the level of death‐associated protein kinase (DAPK) expression by increasing autophagy‐related 7 (Atg7) expression, and then together with DHA to enhance breast cancer cell apoptosis." (PMID 33613116, 2021). "Furthermore, circCDYL upregulates ATG7 and ULK1 expression by sponging miR-1275, thereby enhancing the autophagy levels and malignant progression of breast cancer." (PMID 33234130, 2020). "For example, resveratrol-induced autophagy in human breast cancer cell was independent of Beclin 1 but dependent on ATG7 and ATG12–ATG5." (PMID 28881721, 2017). "Interestingly, araguspongine C-induced autophagic cell death in HER2-overexpressing BT-474 breast cancer cells was characterized by vacuole formation and upregulation of autophagy markers including LC3A/B, Atg3, Atg7, and Atg16L." (PMID 25580621, 2015). "Our results demonstrate that ATG7 expression in fibroblasts has a crucial role in modifying stromal–epithelial crosstalk and disrupting homeostasis in the TME and reveal that ATG7 in fibroblasts and SCARB1 in breast cancer cells may be new indicators for the diagnosis of breast cancer." (PMID 40707430, 2025). "Pharmacological inhibition (through administration of different autophagy inhibitors, such as bafilomycin, 3-methyladenine, and hydroxychloroquine) or genetic (through knockdown of autophagy related 7 (ATG7) but not BECN1) means dramatically impaired the survival of dormant breast cancer cells." (PMID 36701089, 2023). "Additionally, ATG7 knockdown impaired an increase in the migration of MDA-MB-231 cells transfected with TRPM8, suggesting that autophagy mediates the effect of TRPM8 on the migration of breast cancer cells." (PMID 33344232, 2020). "Furthermore, there is a growing body of literature that recognizes the importance of potential applications of autophagy related proteins, including LC3, ATG7, ATG5, Beclin1, and SH3GLB1, as prognostic biomarkers in some tumors, like glioma, breast cancer, and colon cancer." (PMID 33510635, 2020). "Here, our experimental results illustrated that LC3 and LC3B expression, LC3-II/I, ATG5 and ATG7 protein levels were increased, p62 expression and protein level were reduced after PDK4 was depleted in MCF-7 cells, suggesting that PDK4 interference might stimulate autophagy in breast cancer cells." (PMID 38678126, 2024). "Although our planned assessment of mammary cancer was not possible due to early-onset neurodegeneration, the results still predict that Atg7 ablation may impair the fitness and survival of Palb2 mutant cancer cells, thereby delaying or preventing tumor development." (PMID 40396054, 2022).
lung carcinoma (56 papers, 2015 to 2025). "The results showed that the expression of NDC80 was positively associated with the levels of ATG7 in lung cancer, using the GSE102287 and GSE8894 datasets." (PMID 36105209, 2022). "Elsewhere, ATG7 polymorphisms associated with protective or pro‐carcinogenic properties have been reported, and elevation of ATG7 expression is associated with some bladder and lung cancers." (PMID 34725936, 2021). "High expression of Atg10 is associated with poor prognosis for lung cancer, and autophagy gene Atg7 knockout leads to the progression of lung cancer to eosinophilic cell tumors, inhibiting tumor proliferation." (PMID 33194668, 2020). "This stems from the observation that autophagy is highly up-regulated in lung cancer, and inhibition of autophagy by loss of ATG7 expression can suppress tumour cell growth in vitro and in xenograft models." (PMID 31878323, 2019). "This is particularly evident for Ras-driven lung cancers, where ATG7 deletion results in increased mitochondrial mutation load, impaired mitochondrial function, increased production of reactive oxygen species, and a reduction in the cellular nucleotide pool." (PMID 31878323, 2019). "Recent studies showed that deficiency of Atg7 in Kras-driven lung cancer mouse models display suppressed lung tumor growth and prolonged survival, consistent with our finding." (PMID 25897662, 2015). "The level of amino acids and nucleosides significantly decreased in Atg7-deficient lung cancer cells compared to that in autophagy-competent cells cultured in HBSS, while supplementation of glutamine, glutamate or nucleosides rescued the survival of Atg7-deficient lung cancer cells." (PMID 36778128, 2023). "Furthermore, ATG7 was reported to be overexpressed in lung cancer with cisplatin treatment, which causes resistance to apoptosis through cisplatin-induced hydroxyl radicals." (PMID 36105209, 2022). "Furthermore, studies using GEMM showed that Atg7-deficient KRASG12D-driven lung cancer is reduced in proliferation capacity and trigger an immune response." (PMID 34904929, 2022). "In agreement with this, blockade of autophagy using CQ or ATG7 gene knockout lung cancer cells led to increased CD47 protein levels." (PMID 39665172, 2025). "The importance of autophagy in the initiation and/or progression of KRAS- or BRAF-driven lung cancer was revealed through analysis of GEM models in which deletion of key autophagy genes (Atg5 or Atg7) accompanied the initiation of oncoprotein expression." (PMID 39213022, 2024). "MiR-210, an Atg7-targeting miRNA, can strongly enhance lung cancer cell proliferation, while another Atg7-targeting miRNA, miR-138-5p, inhibits the invasion and self-renewal of lung cancer stem-like cells." (PMID 38553562, 2024). "This reduction was accompanied by significantly decreased levels of Beclin 1, ATG7, and ATG5, along with an increased level of p62/SQSMT1 in PC-9GR (T790M mutated lung cancer) cells." (PMID 39272847, 2024). "In lung cancer mice with Atg7 or Atg5 deletions, tumor size decreased compared with wild type Atg7 or Atg5 mice." (PMID 38067169, 2023). "On the contrary, ATG7 was also required for autophagic apoptosis under the treatment of erlortinib in lung cancer with EGFRT790M." (PMID 35690866, 2022). "It is worth noting that the conditional deletion of ATG7 in KRASG12D-driven lung cancers closely correlated with abundant tumor infiltration by CTLs and macrophages." (PMID 35600411, 2022). "For example, ATG7-dependent autophagy suppressed the progression of lung cancer driven by activation of oncogenic HRasV12." (PMID 35690866, 2022). "On the other hand, the dual role of ATG7 in lung cancer is context-dependent, including pro-apoptotic and anti-apoptotic effects." (PMID 35690866, 2022).
lung carcinoma (continued). "In this context, miR-17, miR-138-5p and miR-1236-3p enhances autophagy activity in lung cancer cells via ATG7 targeting (Huang FX." (PMID 35444536, 2022). "It was found that p62 depletion decreased the tumor size in ATG7 deficient mice and eradicated RAS-induced lung carcinoma." (PMID 34944772, 2021). "The present study indicated that cisplatin at the maximum response concentration mediated autophagy through the induction of OH·, which subsequently activated Atg3 and Atg7 and led to apoptosis resistance in human lung cancer H460 cells." (PMID 34321115, 2021). "For example, deletion of Atg5 or Atg7 in Pten-/--driven prostate cancer, KrasG12D- or BrafV600E-driven lung cancer, or KrasG12D-driven pancreatic ductal adenocarcinoma, suppresses tumor growth." (PMID 32308763, 2020). "Consistent with our findings, ATG7 knockout can significantly reduce tumor cell tumorigenicity and promote the transformation of lung cancer into benign tumor." (PMID 29311760, 2018). "The tumor growth promoting benefits of Atg5 or Atg7 loss of expression has also been demonstrated in several experimental models, such as in the BRAFV600E driven lung carcinomas or in the KRASG12D or driven pancreatic cancer." (PMID 26416459, 2015). "We show that NASTRp inhibited oncogenic cell properties through cell cycle arrest with concomitant suppression of tumor-promoting autophagy with down-regulations of Atg5-12 and Atg7, and accumulation of p62 in human lung cancer cell lines." (PMID 25897662, 2015). "In addition, FOXO 3 can activate gene ATG 7 (Autophagy Related 7, ATG7) transcription and activate autophagy, further regulating the occurrence and development of lung cancer." (PMID 41002121, 2025). "In summary, we confirmed that STAT3/FOXM1/ATG7 signalling might be essential for autophagy induced by icotinib in resistant lung cancer cells." (PMID 35690866, 2022). "ATG7 has been observed to promote tumor development, since the knockdown of ATG7 could inhibit the self-renewal and invasion of stem-like lung cancer cells." (PMID 36105209, 2022). "Moreover, in lung cancer stem cells, miR-138-5p mimic can inhibit ATG7-dependent regulation of autophagy and self-renewal." (PMID 35600411, 2022). "Moreover, silencing the Atg5 or Atg7 gene of lung cancer cells harboring active-mutant Rab37 (Q89L) led to decreased autophagy activity and TIMP1 secretion." (PMID 36457117, 2022). "In a similar manner, ATG7 deletion in a lung cancer model inhibited tumor growth." (PMID 34944772, 2021). "In conformity with pro-survival autophagy modulated by OH·, resistance to cisplatin-induced cell death, as well as the overexpression of Atg3 and Atg7 in human lung cancer cells cultured with cisplatin was repressed by pre-incubation the cells with deferoxamine." (PMID 34321115, 2021). "Given that C/D domain of ERβ [145–255 amino acids] is essential to the protein interaction with Bad Lung Cancer Cells43, we explored whether this domain participates in the interaction with ATG7 in SH-SY5Y cells next." (PMID 31332160, 2019).